TNF (tumor necrosis factor)
Diseases named in the same sentence as TNF in open-access papers (continued):
Sharing a sentence is not in itself a finding about the gene and the disease.
breast carcinoma (continued). "Our recent study reported that TNFα selectively induces apoptotic cell death in ERα-positive but not ERα-negative breast cancer." (PMID 34073371, 2021). "We found that the mRNA expression of TNF-α in PBMCs of breast cancer patients was higher than in control but not significant." (PMID 33517609, 2021). "Furthermore, the high concentration of TNF-α and IL-6 mediated JAK2/STAT3 pathway activation to induce phenotypic change into breast cancer cells with SC properties." (PMID 34122412, 2021). "Taken together, these results indicate that TNF-α significantly induced apoptotic cell death in ERα-positive MCF-7 human breast cancer cells, but not in MDA-MB-231 cells." (PMID 32455774, 2020). "Treatment of cancer cells with TNF-α and trastuzumab results in similar decreases in cell viability as trastuzumab-treated cancer cells co-cultured with T-cells in the high overexpressing HER2 + breast cancer cell lines, BT474 and SKBR3." (PMID 33292267, 2020). "Similarly, breast cancer-derived sEVs induce NFκB activation via TLR2 in macrophages resulting in upregulation of IL-6, TNF-α, G-CSF, and CCL2." (PMID 32015297, 2020). "MCM and hCM greatly increased the expression of IL-6, IL-1β, IL-1α, TNF-α, IGF-1, and MCP-1 compared with control at the mRNA levels in MCF-7 and MDA-MB-231 cells, while the little effect on the VEGF expression in mCM treated-breast cancer cells." (PMID 32201525, 2020). "Furthermore, adipocyte- or CAA-secreted factors, including leptin, TNF-α, IL-6, IL-1β, IGFBP-2, LCN2, collagen VI, and others, have also been demonstrated to promote breast cancer cell malignant progression, such as EMT, invasion, and metastasis." (PMID 32242230, 2020). "To investigate whether TNF-α triggers apoptosis in breast cancer cell lines, we treated either MCF-7 or MDA-MB-231 cells with TNF-α for the indicated time and adapted various experiments to assess apoptotic cell death." (PMID 32455774, 2020). "Also, we describe TNFα role in immune response against tumors and in chemotherapy, hormone therapy, HER2-targeted therapy and anti-immune checkpoint therapy resistance in breast cancer." (PMID 32391269, 2020). "There might be a reduced inflammatory process via a reduction in TNF-α, IL-6, IL-18, and CRP expression in breast cancer mice that were subjected to moderate intensity exercise." (PMID 32309219, 2020). "In conclusion, we demonstrate that TNF-α launches the cells through a stemness differentiation via up-regulation of TAZ transcription through a non-canonical NF-κB pathway in human breast cancer cell lines." (PMID 32019974, 2020). "Postmenopausal breast cancer survivors were subjected to aerobic exercise for 24 weeks, but there was no change in TNF-α." (PMID 32309219, 2020). "For instance, it was reported that TNFα induces a cytotoxic effect in luminal breast cancer cell lines in absence of ubiquitin editing enzyme TNFα-induced protein 3 (TNFAIP3 also called A20), but this protein has a wide range of effects in different tissues." (PMID 32391269, 2020). "Results showed that serum PD-1 and PD-L1 levels were significantly higher in cats with HER2-positive (p = 0.017; p = 0.032) and triple negative (TN) normal-like mammary carcinomas (p = 0.004; p = 0.015), showing a strong positive correlation between serum CTLA-4 and TNF-α levels." (PMID 32481540, 2020). "For example, TNF-α induces LOX expression via the reactive oxygen species-activated nuclear factor-kappaB (NF-κB)/extracellular signal-related kinase (ERK) pathway, thus promoting the progression of breast cancer metastasis." (PMID 33123472, 2020). "Therefore, we assessed the effect of TNF-α, a stimulant of NF-κB pre-treated with AIM on breast cancer cells." (PMID 32455624, 2020).
breast carcinoma (continued). "The analysis of two breast cancer cell lines, MDA-MB-231 and MCF-7, reveals RID's inhibitory capacity of the TNF-α-induced signaling pathway that activates NF-κβ and IL-8 secretion to the extracellular medium and by the reduction of neovascular processes in endothelial cells HMEC1 in culture." (PMID 32655311, 2020). "PRLR-DbsAb in vitro could recruit and activate T cells to promote the release of Th1 cytokines IFN- γ and TNF- α, which could kill PRLR expressed breast cancer cells." (PMID 32398042, 2020). "Additionally, in breast cancers, a strong correlation has been reported between LVI and genes controlling ECM degradation, angiogenesis, neovascularization, and tumor necrosis factor." (PMID 32722116, 2020). "TNFα can also stimulate cancer cells proliferation through the p42/p44 MAPK pathway mediated by TNFR1 and TNFR2 independently of NF-κB, establishing an alternative pathway to breast cancer proliferation." (PMID 32391269, 2020). "In addition to TNF-α, PrPC is also involved in the resistance to adriamycin (ADR) and TRAIL-mediated cell death in breast cancer cells as down-regulation of PrPC increased the sensitivity to these molecules." (PMID 33276687, 2020). "Therefore, we aimed to investigate the effects of exercise on inflammatory cytokines interleukin (IL)-6, IL-18, tumor necrosis factor-α (TNF-α), and C-reactive protein (CRP) in a breast cancer mouse model." (PMID 32309219, 2020). "Moreover, TNFα activates the MAPK/ERK signaling pathway and subsequently promotes the migration of breast cancer cells through the upregulation of MMP9, MMP14, and MMP2 in the lipid rafts." (PMID 32986377, 2020). "Although NLRP3 mRNA expression levels were increased in RT-R-MDA-MB-231 cells compared to MDA-MB-231 cells, the protein levels were not very different and were not responsive to TNF-α or ATP treatment in either type breast cancer cell." (PMID 32397236, 2020). "As TNF-α is considered as a potential candidate for virotherapy in cancer patients, we have further analyzed the expression level for TNF-α in NDV treated 4 T1 breast cancer model." (PMID 30947706, 2019). "In conclusion, these findings suggest that the combination treatment of Doxorubicin, E2 and TNFα may be involved in decreasing the expression and activity of ESR1, potentially enhancing the chemotherapy efficacy in ER positive breast cancers." (PMID 31645610, 2019). "By analyzing the data from 719 breast cancer samples in which the luminal is 566, Her2 + is 37, and TNBC is 116, we found that the expression of IL-1β and TNF-α showed a significant increase in TNBC compared with luminal and Her2 + breast cancers (p < 0.005 by the two-sided Student’s t-test)." (PMID 31602400, 2019). "However, our results for let-7-5p are in agreement with those observed for let7, let-7a, and let-7d that down-regulate IL-6 and IL-10 directly or TNF, IL-6, and IL-1β indirectly in MCF10A, fibroblasts, and breast cancer cells." (PMID 31694049, 2019). "This review generally provides a background for nanoparticles as potential drug delivery agents for immunomodulators and further discusses in depth the potential of TNF antagonists delivery to modulate TNF-TNFR2 interactions and inhibit breast cancer progression." (PMID 31239840, 2019). "We demonstrate that secretomes from metastatic breast cancer cells differentially regulate the lung and brain, promoting a tumor-supportive lung microenvironment with both elevated CD73 expression and decreased TNFα expression." (PMID 31105883, 2019).
breast carcinoma (continued). "CAAs secrete more chemokine (C–C motif) ligand 2 (CCL2), chemokine (C–C motif) ligand 5 (CCL5), interleukin-1β (IL-1β), interleukin-6 (IL-6), tumor necrosis factor-alpha (TNF-α), vascular endothelial growth factor (VEGF), leptin, etc., which can promote the invasion and metastasis of breast cancer." (PMID 31500658, 2019). "Furthermore, we also found that supplement of TNF-α reversed the effects of Oroxylin A on the cell proliferation, invasion, migration, and EMT in breast cancer cells." (PMID 31341911, 2019). "When tumor cells from the Luminal-A breast cancer subtype were exposed to TME-enriched conditions consisting of TNFα and endothelial growth factor (EGF), the breast cancer cell population became enriched for a CD44+CD29+ CSC phenotype with increased metastatic properties." (PMID 31450577, 2019). "Conditioning of macrophages with TNF-α was necessary in order to induce notable proliferation of ER+ breast cancer cells in the absence of estradiol or presence of antagonists; i.e., nonconditioned THP-1 macrophages had no such effect." (PMID 30736340, 2019). "Moreover, TNF-α stimulated MSCs released more CXCL9, CXCL10, and CXCL11, which are the ligands of CXCR3, to increase cell migration of co-cultured breast cancer cell line MDA-MB-231 via the NF-κB signaling pathway." (PMID 31130595, 2019). "Alteration in the activity of transcription factors could be critical for the development and maintenance of radioresistance in breast cancer by control genes of the survival pathways, such as the RAS‐MAPK and TNF pathways." (PMID 30938061, 2019). "For example, tumor necrosis factor alpha (TNF-α) and interleukin-1β (IL-1β) can upregulate the expression of GLI1 through the nuclear factor kappa light chain enhancer of activated B cells (NF-κB) pathway in pancreatic and breast cancer cells." (PMID 30759860, 2019). "Transcriptional linear correlations between aromatase and the cytokines TNFα and IL-6 have been reported in patient breast cancer tissue, but not in adjacent non-cancerous tissue." (PMID 29463044, 2018). "These elevated circulating cytokines (IL-6, IL-8, TNF-α, and vascular endothelial growth factor; VEGF), exert effects at distant sites, that can promote breast cancer development through upregulation of inflammatory mediator synthesis and increased immune cell infiltration as well as angiogenesis." (PMID 30619088, 2018). "SNAIL1 activates expression of CCL2, CCL5, IL-6, TNFα, and IL-8 in head and neck cancer cells and overexpression of SNAIL1 in 4T1 cells increased infiltration of M2-like macrophages and promoted metastasis in a breast cancer orthotopic model." (PMID 29593211, 2018). "TGFB1, TNF, IL1B and IL6 are inhibited by ligand-bound AhR in ERα-positive breast cancer cells." (PMID 29320557, 2018). "Additionally, recent evidence suggests that TNFα, IL-6, and TGFβ secreted from TCR-activated T cells induces EMT in inflammatory breast cancer cells." (PMID 29805773, 2018). "In osteolytic metastasis produced by a large majority of breast cancer cells, the osteoclast activity is stimulated by cancer cells that release interleukin-1 (IL-1), IL-6, PTHrP, prostaglandin E2 (PEG2), TNFalpha (Tumor Necrosis Factor), VEGF (Vascular Endothelial Growth Factor), and M-CSF." (PMID 29642618, 2018). "COX-2, TNF-α, VEGF-A and IL-6 are tumorigenic genes that are elevated in breast cancer." (PMID 30155724, 2018). "Cyclooxygenase-2 (COX-2), tumor necrosis factor-alpha (TNF-α), vascular endothelial growth factor (VEGF) and IL-6 are all inflammation mediators that play critical roles in metastasis and progression of breast cancer." (PMID 30155724, 2018). "Strikingly, we found that TNF-α was able to up-regulate HBXIP through driving a positive feedback loop of NF-κB (and/or p38)/p-STAT3/HBXIP/TNFR1, resulting in the enhancement of growth of breast cancer." (PMID 28938560, 2017).
breast carcinoma (continued). "Together, our findings indicate an important role of TNFα-IKK-YAP/p65-HK2 signaling axis in the process of inflammation-driven migration in breast cancer cells, which reveals a new molecular link between inflammation and breast cancer metastasis." (PMID 28945218, 2017). "As expected, we observed that TNF-α could activate STAT3 via NF-κB and/or p38 signaling, leading to the up-regulation of HBXIP in breast cancer cells." (PMID 28938560, 2017). "Furthermore, silencing of TNFR1 by siRNA significantly inhibited the proliferation of MDA-MB-468 or SKBR-3 cells induced by TNF-α, suggesting that TNF-α promotes cell proliferation of breast cancer through activating TNFR1." (PMID 28938560, 2017). "YAP mediates TNFα-induced expression of HK2 and glycolysis in breast cancer cells." (PMID 28945218, 2017). "However, the significance of TNF-α in regulation of TNFR1/NF-κB (and/or p38)/p-STAT3 in breast cancer is elusive." (PMID 28938560, 2017). "In MDA-MB-231, ER negative breast cancer cells, TNFα exposure induced IκBα degradation but to a lesser extent than that observed in the MCF7 cells and no increase in phosphorylation of p65 (p-p65) was observed." (PMID 28423692, 2017). "Furthermore, even in the early stages, breast cancer patients have increased serum levels of prostaglandin E2 (PGE2) and proinflammatory cytokines such as tumor necrosis factor alpha (TNF-α), interleukin (IL)-1β and IL-6." (PMID 29061183, 2017). "Moreover, TNF-α showed cytotoxic effects and induced apoptosis in MCF-7 and Hs578T breast cancer lines." (PMID 29202842, 2017). "While in the serum of healthy women TNF-α is generally not detected, clinical studies have reported high levels of this cytokine in patients with breast cancer." (PMID 29202842, 2017). "Co-incubation with TNF-α for 48 h led to a significant increase in CD47 expression on MCF7 breast cancer cells (already CD47Hi) but only a slight increase on nontumorigenic breast cancer MCF10 cells (CD47Med) and the hepatoma cancer cell line HepG2 (CD47Lo)." (PMID 28378740, 2017). "Although pro-inflammatory cytokines such as IL-1β and TNFα induce IL-6 production from innate immune cells during acute inflammation, this is not the case in human breast cancer cells." (PMID 27609180, 2016). "Our experiments show only partial inhibition of VEGF induction by TNF-α neutralizing antibody, with no statistical significance, indicating TNF-α is not the sole/major regulator of VEGF production in co-cultures of breast cancer cells with macrophages." (PMID 27514308, 2016). "In recent years, the treatments of breast cancer focus on the identification of cytokines as prognostic factors, including several interleukins (IL-1, IL-6, IL-10), transforming growth factor-β (TGF-β), tumor necrosis factor-a (TNF-a) and so on." (PMID 27231908, 2016). "It was found that B7-H3Bi-armed ATC secreted more IFN-γ, TNF-α and IL-2 than unarmed ATC, and had enhanced cytotoxic activity against a wide range of human cancer cells, including lung cancer, breast cancer, colorectal cancer, pancreatic cancer, cervix cancer, prostate cancer, and glioblastoma." (PMID 27121051, 2016). "Th1 cell production of the cytokines interferon gamma (IFNγ) and TNFα can enhance MHC class I expression, PD-L1 expression, augment apoptosis and tumor senescence, and enhances growth inhibition of many anti-breast cancer agents, including anti-estrogens and HER-2 targeted therapies." (PMID 27766079, 2016). "Macrophage secretion of pro-inflammatory cytokines IL-6 and TNF-α, which increase MDSC accumulation, was also reduced by WA, additionally WA delayed tumor progression with reduction of the accumulation of G-MDSCs in 4T1 mammary carcinoma bearing mice." (PMID 27886105, 2016). "RANKL and TNF-α production was significantly increased in bone fragments cultured with MCF-7 breast cancer cells in comparison to bone fragments cultured without cancer cells, both in normoxic and hypoxic conditions." (PMID 27765913, 2016).
breast carcinoma (continued). "On the other hand, IL6 and tumor necrosis factor (TNF)α increased STS activity in a breast cancer cell line MCF7 not changing the mRNA levels, which suggested posttranslational modifications via STS glycosylation." (PMID 26924986, 2016). "Further, we establish TNF signaling as an important regulator of early luminal breast cancer formation and identify the requirement of Tnfr1 for mediating breast cancer suppression seen in the absence of Timp3." (PMID 25807548, 2015). "Of note, although TNF-α and IL-1β increased the proteoglycan degradation, autophagy was induced by TNF-α and IL-1β in chondrocytes, AF cells, fibrosarcoma L929 cells and breast cancer cells." (PMID 26165348, 2015). "Here, we determine the role of TIMP3 through TNF in different compartments and during different stages of a breast cancer mouse model that is independent of ErbB/EGFR growth factor release." (PMID 25807548, 2015). "The regulation of TNF signaling by TIMP3 may comprise an important step in tumor development as revealed in both PyMT and Neu models of breast cancer." (PMID 25807548, 2015). "IL-6, MCP-1, and TNFα are elevated in mouse wound healing models but not in this breast cancer model, except for IL-1β, elevated in both models." (PMID 26113869, 2015). "In breast cancer cell lines, short term exposure to DHTS influences mRNA stability and translational efficiency of TNF in a HuR-dependent manner and also other functional readouts of its post-transcriptional control, such as the stability of selected pre-mRNAs." (PMID 26553968, 2015). "In addition, elevated expression of PTX3 by TNFα led to enhanced OC formation, implying the distinct role of PTX3 in osteolytic bone metastasis of breast cancer cells." (PMID 24457902, 2014). "This process is triggered by signals, such as TGF, TNF and Wnt, received from the microenvironment, and it has recently been proposed that fibronectin has an essential role in the establishment of EMT in breast cancer cells." (PMID 25208219, 2014). "Microarray analysis comparing the populations in which the reporter construct is active versus inactive showed that positive cells expressed higher mRNA levels of cytokines (IL-8, IL-6, TNF) and genes (such as ATF3, SNAI2, and KLF6) previously related with the CSC phenotype in breast cancer." (PMID 25414831, 2014). "Moreover, in breast cancer cell lines, blocking TNFRSF1A or TNFRSF1B with specific antibodies impairs tumor survival signaling and the biological function of TNF-α." (PMID 25010932, 2014). "Given that the pro-inflammatory cytokine TNFα up-regulated expression of PTX3, we hypothesized that increased production of PTX3 in breast cancer cells may support cell proliferation and migration." (PMID 24457902, 2014). "We addressed the elevated expression and secretion of PTX3 in breast cancer cells with bone metastatic properties compared to non-bone metastases of breast cancer, and its related regulation by TNFα." (PMID 24457902, 2014). "Nevertheless, the group of premenopausal patients with combined low 25OHD and high TNFα levels were at the highest odds of ER negative vs. ER positive breast cancer, much higher than the expected additive effects from each analyte." (PMID 24473087, 2014). "To examine the molecular mechanism by which senescent MSCs stimulate breast cancer cell proliferation and migration, we assessed four cytokines (IL-6, VEGF, HGF and TNF-α) that are closely related to tumor progression by enzyme linked immunosorbent assay (ELISA)." (PMID 25419563, 2014). "TNF-α, when combined with WA or Cel, activated caspase-3 and -9 and downregulated XIAP in a dose-dependent manner, leading to induction of apoptosis in MDA-MB-231 breast cancer cells." (PMID 25419573, 2014).